FAM174C (family with sequence similarity 174 member C )
Synonyms: C19orf24
Gene: Protein-coding gene on chromosome 19 (1,275,530 to 1,279,244, forward strand). Ensembl gene ENSG00000310576.
Gene Ontology:
Cellular component: cytoplasm; extracellular region; membrane
Homologues: Orthologues: chimpanzee FAM174C (99% identical), macaque FAM174C (86% identical), dog FAM174C (77% identical), pig FAM174C (77% identical), guinea pig FAM174C (65% identical), mouse Fam174c (55% identical), rat Fam174c (53% identical), tropical clawed frog fam174c (36% identical), zebrafish fam174c (31% identical).